KRT7 (keratin 7)
Diseases named in the same sentence as KRT7 in open-access papers (continued):
Sharing a sentence is not in itself a finding about the gene and the disease.
tumor (continued). "The tumor cells exhibited positivity for cytokeratin 7 (CK7) and caudal type homeobox 2 (CDX-2) but negativity for cytokeratin 20 (CK20), paired box 8 (PAX8), NK3 homeobox 1 (NKX3.1), and thyroid transcription factor 1 (TTF-1)." (PMID 39350874, 2024). "KRT7 plays an important role in preserving tissue architecture, tumor progression, invasion, and metastasis." (PMID 38877052, 2024). "Single-cell analysis further revealed that MET, MUC16, and KRT7 were mainly expressed in cancer cells in PC tumour microenvironment." (PMID 37815881, 2023). "Hepatic progenitor cells and cholangiocytes have the tumor markers cytokeratin 7 (CK7) and cytokeratin 19 (CK19), whereas normal hepatocytes do not." (PMID 37726886, 2023). "The organoids’ morphology was found similar to that of the primary tumor, and organoids expressed typical CP markers, including cytokeratin 7 (CK7), CD133 and catenin beta 1 (CTNNB1)." (PMID 37614709, 2023). "These tumour cells were weakly positive for cytokeratin 7, thus imparting a biliary phenotype, while showing reduced expression of CPS1, a hepatocyte-specific marker." (PMID 37946160, 2023). "After determining the tumor cells by desmin, marking intact glandular tissue with cytokeratin 7 (CK7) and excluding macrophages by CD68, the distribution and localization of GALNT14 was investigated." (PMID 37671061, 2023). "Dermatohistopathological examination of skin biopsies revealed a diffuse and nodular infiltrate of pleomorphic atypical tumour cells with strong expression of cytokeratin 7 and PAX8, also detectable within lymphatic vessels." (PMID 37013123, 2023). "Both PD-L1-negative and PD-L1-positive patients showed clusters of tumor cells expressing KRT7, KRT8, and KRT18." (PMID 36674951, 2023). "Cytokeratin 7 (CK7) was chosen to select for tumor cells as it is highly expressed in mesothelioma cancer cells across patients." (PMID 37468581, 2023). "Clusters 2, 6, and 11 expressed Keratin genes (Krt7, Krt8, and Krt18), suggesting their potential tumor origin." (PMID 37055410, 2023). "Immunohistochemistry showed that the tumor cells expressed cytokeratin 7, P63, P40, CK5/6, Pan Cytokeratin (PCK), and epithelial membrane antigen, whereas they were negative for thyroid transcription factor-1, napsin A, CD10, vimentin, and smooth muscle actin." (PMID 37352028, 2023). "The results showed there were some Keratin 7-positive cells in the lymph node, suggesting gefitinib treatment adversely triggered the metastasis of some drug-resistant tumor cells and CNOT3 depletion prevented it." (PMID 37919290, 2023). "The immunohistochemistry staining showed immunoreactivity to keratin 20 (CK20) in the sections of tumors from miBx, miPa, and miPk cells while only miPk tumor sections were immunoreactive to keratin 7 (CK7)." (PMID 35063003, 2022). "When restricting disseminated tumor cell detection to keratins KRT7 and KRT8, the prognostic information was substantially stronger (p = 1 × 10–6; HR = 22, and p = 2 × 10–5; HR = 7.7, respectively)." (PMID 35659265, 2022). "Immunohistochemically, the tumor cells were positive for cytokeratin 7 (CK7) and focally positive for α-methylacyl-coenzyme A racemase (AMACR, also called p504s) but negative for thyroid transcription factor-1." (PMID 35449090, 2022). "The tumor cells from the previous resection were positive for cytokeratin 7(CK7), CAM5.2, p63, and CK5/6." (PMID 35168684, 2022). "Immunohistochemistry for the tumor cells was positive for pancytokeratin and cytokeratin 7, partially positive (up to 20%) for cytokeratin 20 and CDX2, and negative for estrogen receptors, monoclonal carcinoembryonic antigen (CEA), and synaptophysin." (PMID 35664390, 2022).
tumor (continued). "By IHC, the KRT7 expression was only detected in the basal cell compartment from all tumor-adjacent benign glands with rabbit monoclonal SP52-KRT7 antibody." (PMID 35406395, 2022). "Immunohistological staining with the human-specific cytokeratin-7 (CK7) antibody perfectly overlapped with the HE staining of tumor cells, strongly suggesting that these tumors were of human origin." (PMID 36497214, 2022). "KRT7 expression is generally restricted to epithelia and neoplasms, and its rate of positivity in CCA is 93%." (PMID 36300097, 2022). "Observation of KRT7 staining was augmented in benign proximal peri-tumoral glands adjacent to the tumor compared to distal benign glands, obtained from a tissue block where no cancer was detected or transitional zone." (PMID 35406395, 2022). "This is well expressed by the loss of Cytokeratin 7 (CK7), Thyroid transcription factor-1 (TTF1) and Mucin1, cell surface-associated (MUC1) IHC staining of the tumor." (PMID 34440689, 2021). "The tumor marker KRT7 is found to be upregulated in a small population of squamous columnar (SC) junction cells, as compared to other squamous and columnar cells of the transformation zone." (PMID 35008799, 2021). "Haematoxylin and eosin (HE) staining of the primary surgically resected tumour sample revealed typical adenocarcinoma histology with positive IHC markers including Napsin A, cytokeratin 7 (CK7), thyroid transcription factor‐1 (TTF‐1) and ALK (Ventana)." (PMID 34541785, 2021). "The tumor cells were immunohistochemically positive for anti-cytokeratin 7 and anti-hepatocyte paraffin 1 antibodies." (PMID 33566306, 2021). "Gordon‐Sweet's silver staining and cytokeratin 7 staining clearly showed that the tumor cells and liver parenchyma were in close approximation, without compression of the liver cell plates." (PMID 32135041, 2020). "The sTRAIL produced by AD-MSCs that infiltrated the tumor stroma was able to significantly inhibit tumor growth in vivo: substantial reductions in tumor mass and in cytokeratin-7-positive cells, as well as an antiangiogenic effect, were observed." (PMID 33117154, 2020). "It revealed that the VOA1066 primary tumor cells lost the expression of four epithelial markers including ER, cytokeratin-7 (CK7), EMA and PAX8, which were retained in the epithelial cells of the adjacent normal endocervix tissue." (PMID 33052929, 2020). "To further investigate the histopathological feature of tumor organoids and how this relates to parental tissues, we performed immunohistochemistry for pancreatic markers KRT7, MUC1 and MUC5AC, and the intestinal markers KRT20 and MUC2." (PMID 33327494, 2020). "Tumor cells stained with the tumor marker Cytokeratin 7, were dramatically reduced only in tumors from mice treated with CD44v6.CAR T cells, while no reduction was observed in animals treated with control cells." (PMID 32117253, 2020). "The tumor cells express cytokeratin 7 (CK7), cytokeratin 5-6 (CK5-6), cancer antigen 125 (CA125), estrogen (ER), progesterone (PR), Wilm's tumor gene (WT1), paired box gene 8 (PAX8), Ber-EP4, and epithelial membrane antigen (EMA)." (PMID 33062370, 2020). "In line with the proposed signaling functions, we recently demonstrated that KLK4, in combination with KLK5, 6, and 7, regulates gene expression of other tumor-relevant genes such as MSN (encoding moesin), KRT7 and KRT19 (encoding keratins 7 and 19)." (PMID 30811511, 2019). "The TMP panel included 7 proteins routinely used in diagnostic IHC including cytokeratins (KRT5 and KRT7), markers of stratified epithelia (P63), mesenchymal (Vimentin) and neuroendocrine (CHGA, SYP) differentiation, and primary tumour origin (TTF1)." (PMID 31537838, 2019). "Immunohistochemical study revealed tumor cells positive for cytokeratin 7 (CK7), cytokeratin 20 (CK20), p63, epithelial membrane antigen (EMA), uroplakin III, and GATA-3." (PMID 31699107, 2019).
tumor (continued). "sTRAIL released by AD-MSC relocated into the tumor stroma was able to significantly counteract tumor growth in vivo with a significant reduction in tumor size, in cytokeratin-7+ cells and by an anti-angiogenic effect." (PMID 30742129, 2019). "The cytokeratin antibodies (anti-keratin 7 and 18) were used to distinguish epithelial/tumor cells from stromal cells." (PMID 31159419, 2019). "In contrast, only three luminal markers showed immuno-staining in the tumor transplants (KRT7, KRT19, and CD24)." (PMID 30550540, 2018). "To exclude the influence from the tumor microenvironment, we also stained the serial section with both cytokeratin 7 (CK7) and S100A8." (PMID 30456203, 2018). "These NSCLCs express proteins such as cytokeratin-7 (CK7) and thyroid transcription factor-1 (TTF1) which are diagnostic markers of the tumor." (PMID 29415661, 2018). "The staining of KRT7 was similar in both the well-differentiated and less differentiated areas of tumor for the tumors generated from Cd2+- transformed UROtsa cells." (PMID 30550540, 2018). "Tumor cell are not only strongly reactive with mitochondrial antigen, but also express cytokeratin AE-1/AE-3, cytokeratin 7, CEA, EMA, and p63." (PMID 29489937, 2018). "Immunohistology revealed the same findings as compared to the biopsy specimen including a strong expression of keratin 7 by all tumor cells." (PMID 29145864, 2017). "In immunohistochemical findings, the tumor cells were positive for pan-cytokeratin, cytokeratin 7, epithelial membrane antigen, gross cystic disease fluid protein-15, and androgen receptor (AR), confirming the apocrine origin of the tumor." (PMID 27668109, 2016). "The tumour cells demonstrated positive staining for cytokeratin (AE1/AE3) with keratin 7 (CK7) staining the luminal cells in the glandular structures." (PMID 27429819, 2016). "An immunohistochemical battery showed the tumor cells to be positive for cytokeratin 7, patchy positive for CA19.9, and patchy CDX2 positive; cytokeratin 20, mesothelial markers, and breast/skin adnexal markers were negative." (PMID 27999702, 2016). "Expression was compared by signal intensity in microarrays and staining of histological sections of these tumours using antibodies to p63, Krt5, Krt7 and Vil1." (PMID 26783136, 2016). "These tumours are positive for cytokeratin 7 (CK7) with focal expression of carcinoembryonic monoclonal antibody (CEA-M), CA19-9, MUC1, B72.3, and MUC5AC." (PMID 26421012, 2015). "The tumor cells were immunoreactive for cytokeratin 7 (CK7), thyroid transcription factor-1 (TTF-1), and napsin A and were negative for CD20, CDX2, P63, chromogranin, synaptophysin, and CD56." (PMID 26425638, 2015). "Immunohistochemically, the inner tumor region of tubuloductal structures stained strongly positive for cytokeratin 7 (CK7) and the outer tumor cells were weakly positive for CK7." (PMID 24711821, 2014). "More recently, CK19 levels together with CK7 (cytokeratin 7) have been investigated again using an HCC-TMA and found to be significantly associated with tumor grade and AFP levels (alpha-fetoprotein)." (PMID 27600338, 2014). "Immunohistochemically, all tumour cells (both foamy and eosinophilic cells) expressed diffusely cytoplasmic cytokeratin 7, cytokeratins 5/6 and calretinin." (PMID 24066870, 2013). "Cytokeratin 7 and cytokeratin type 1 (AE-1 clone) were expressed homogenously in the cell cultures and in the tumour tissue." (PMID 22666492, 2012).
tumor (continued). "The tumor showed diffusely positive reactivity with cytokeratin (Pan), cytokeratin 19, cytokeratin 5/6, cytokeratin 7, EMA, vimentin, CD56, and NSE and also showed variable reactivity with glial fibrillary acidic protein (GFAP) and VEGF." (PMID 22472343, 2012). "This tumor we report was positive for cytokeratin (Pan), cytokeratin 19, cytokeratin 5/6, cytokeratin 7, and epithelial membrane antigen, so it is easy to differentiate them by immunohistochemistry." (PMID 22472343, 2012). "In some tumor cells, limited immunoreactivity for cytokeratin 7, epithelial membrane antigen and carcinoembryonic antigen was noted." (PMID 19918544, 2009). "As reflected by immunohistochemistry and western-blot analyses, although TOV-2223 tumor tissue expressed Krt7, the corresponding cell line seems to have lost the capacity to express this particular keratin." (PMID 18507860, 2008). "Immunohistochemically, tumor cells were positive diffusely for Cytokeratin 7, and focally for Cytokeratin 20 and Thyroid Transcription Factor-1." (PMID 18823534, 2008). "Both TOV-1946 and OV-1946 cell lines expressed Krt7 and hence mirror keratin expression observed in vivo in the original tumor." (PMID 18507860, 2008). "We further extended the analysis to include KRT7 immunohistochemistry of normal bladder, Ta and T2-4 tumours." (PMID 16265353, 2005). "Again, we found strong KRT7 transcript upregulation in Ta tumours (N=48), as well as in T2-4 tumours (N=24) compared to normal bladder biopsies." (PMID 16265353, 2005). "Immunohistochemically the tumor strongly reacted with synaptophysin, chromogranin, calcitonin, keratin 7, and NSE." (PMID 16048646, 2005). "A total of 102 samples of adenocarcinoma were identified from our tumour registry and evaluated for cytokeratin expression using cytokeratin 7 and 20 immunostains." (PMID 12085180, 2002). "Previous studies have shown that KRT7 mRNA expression measured by qRT‐PCR could be a sensitive technique for the molecular detection of KRT7‐positive circulating tumor cells (CTCs) resembling A549 cells in peripheral whole blood of LUAD patients." (PMID 41488744, 2026). "The tumor cells showed patchy positivity for cytokeratin 7 (CK7), strong cytoplasmic staining for alpha-methyl acyl-CoA racemase (AMACR), and were negative for PSA, cytokeratin 20 (CK20), GATA-binding protein 3 (GATA3), tumor protein 63 (p63), and caudal-type homeobox transcription factor 2 (CDX2)." (PMID 40662003, 2025). "Among epithelial populations, we identified tumor cells (expressing Cd44, Ccnd1, Plau, Krt7), luminal alveolar (AV) cells (expressing Kit, Ehf, Csn3, Ltf), luminal hormone-sensing (HS) cells (expressing Prlr, Esr1, Pgr), and myoepithelial cells (expressing Myh11, Mylk, Myome1)." (PMID 41332581, 2025). "The tumor cells were immunoreactive for cytokeratin-7 (CK7), p63, AR (1+), and Her-2 (1+)." (PMID 39301249, 2024). "Importantly, hepatocytes derived from tumour samples consistently showed high expression of malignant genes KRT7 and PCNA." (PMID 37994257, 2024). "Results showed the correlation between CXCL12 and differentiation grade, CEA and TTF-1 protein expression, CD44v6 was associated with tumor stage, chromogranin expression whereas HIF1A and KRT7 were significantly associated with CEA protein expression in the metastatic tissues." (PMID 38877052, 2024). "We found that in the tissue cohort CXCL12 expression was strongly correlated with differentiation, CEA & TTF-1 protein expression, CD44v6 was associated with tumor stage and chromogranin protein expression and HIF1A & KRT7 showed positive correlation with CEA expression alone." (PMID 38877052, 2024). "We further analysed the correlation between CXCL12, CD44v6, HIF1A, TGFBR2 and KRT7 expression in metastatic tumor tissues & exosomes with sex, age, habit, Tumor Differentiation grade, TNM stage, EGFR mutation status, AE1, Chromogranin, CDX2, CEA, CK20, TTF-1 & CK7." (PMID 38877052, 2024).
tumor (continued). "Thus, EPCAMhigh tumor spots more often demonstrated the expression of such epithelial markers as KRT7, KRT8, and KRT18 compared to EPCAMlow and EPCAM-negative clusters." (PMID 39456890, 2024). "Moreover, Immunohistochemistry revealed that the human chorionic gonadotropin, cytokeratin 7, and EpCAM expression levels were similar to those in the primary tumour." (PMID 37957624, 2023). "Some tumor cells were labelled in the immunohistochemical reaction for cytokeratin 7 (CK7)." (PMID 35545685, 2022). "Our results showed that the expression levels of KRT7 were varied among different malignant clusters and established cell lines, which may confer different degrees of the deformability and motility to tumor cells." (PMID 35974300, 2022). "FTE markers (PAX8, KRT7) were highly expressed in all subclusters of epithelial cells, indicating that the tumor may originate from fallopian tube." (PMID 36248860, 2022). "Immunohistochemistry showed the tumor cells were positive for cytokeratin 7 (CK7), CEA, CK (AE1/AE3, CAM5.2), and thyroid transcription factor-1 (TTF-1) and negative for CK20, estrogen receptor, progesterone receptor, CD5, CD10, neuron-specific enolase, P40, PAX8, GATA3, PSA, CDX2, and NapsinA." (PMID 33101670, 2020). "Immunohistochemically, the tumor was strongly positive for keratin 7 (CK7) and pankeratin AE1/AE3, and alpha 1 antichymotrypsin; negative for synaptophysin and chromogranin A, CDx2, CK20, S100, carcinoembryonic antigen (CEA), MUC 2, MUC5AC, and somatostatin; and in part positive for CA19-9." (PMID 29145864, 2017). "The tumor was biopsied via bronchoscopy and found to be a poorly differentiated carcinoma, which was strongly positive for cytokeratin 7 (CK7), carcinoembryonic antigen (CEA), and thyroid transcription factor-1 (TTF-1) but negative for CK20, estrogen receptor, and progesterone receptor." (PMID 29900025, 2017). "The presence of OvCa+/CD45- CTCs at baseline was associated with significantly lower levels of KRT5 (mean lg2 transformed gene expression 1.12 vs. 0.10, p = 0.040) and KRT7 (mean lg2 transformed gene expression 1.34 vs. 0.36, p = 0.034) gene expression in the corresponding tumor tissue samples." (PMID 29290959, 2017). "Also, colonies expressed pancreatic acinar (PTF1a, amylase, trypsin) and ductal markers (KRT7) and reliably formed subcutaneous xenografts that faithfully recapitulated the original human tumor histology." (PMID 28526679, 2017). "Immunohistochemistry showed that tumor cells expressed cytokeratin 7, pancytokeratin, and MOC-31." (PMID 25442640, 2014). "A few tumor cells were positive for cytokeratin 7 (CK7) and CK20." (PMID 24083046, 2013). "Immunostaining indicated elevated levels of tumor marker, cytokeratin 7 (CK7)." (PMID 22188664, 2011). "The carcinomatous tumor cells with pleomorphic nuclei and abundant cytoplasm arranged in solid sheets and nests were positive for hepatocyte paraffin-1 (HepPar-1) staining and cytokeratin-7 (CK7) staining." (PMID 20500842, 2010). "FatiGO+ analysis showed that tumor libraries had significantly more expressed genes related to "cell organization and biogenesis" (GO:0016043), KRT7, PDIA3, PPGB and TRAPPC5 (p = 0.005); and "ligase activity" (GO:0016874), UBE2S and MTHFD1 (p = 0.028) than normal libraries." (PMID 18302799, 2008). "Immunohistochemically, the tumor cells showed strong positivity for Cytokeratin 7 (CK7)." (PMID 18823534, 2008). "In addition, the KRT7 protein level in most T2-4 tumours (N=6) was also increased, compared to normal biopsies (N=8)." (PMID 16265353, 2005). "Moreover, cytokeratin 7 (CK7) was stained to clearly delineate the EMPD tumor cells." (PMID 32824340, 2020).